DCN (decorin)
Diseases named in the same sentence as DCN in open-access papers (continued):
Sharing a sentence is not in itself a finding about the gene and the disease.
ganglioglioma (1 paper, 2023). A well differentiated, slow growing neuroepithelial neoplasm composed of neoplastic, mature ganglion cells and neoplastic glial cells. "Co-expression of CD34, PAX6, SOX2, and MSI1 (after stringent counter selection against vascular cells using PECAM1, VWF, DCN, and COL1A2), was particularly strongly associated with ganglioglioma neoplastic cell stemness." (PMID 36966348, 2023).
gastric tumor (1 paper, 2021). "The results indicated that DCN and TGFβ formed a complex and possibly interacted with each other in normal tissues, whereas ASPN and TGFβ predominantly interacted with each other in gastric tumor tissues." (PMID 34379688, 2021).
glomerular diseases (1 paper, 2015). "In contrast to the 4/2,4-di-O-sulfated DS domain, the IdoA-Gal-NAc4S DS domain, recognized by the antibody GD3A12, and decorin were not expressed in the glomeruli of patients with glomerular diseases." (PMID 26322947, 2015).
Granuloma (1 paper, 2019). A compact, organized collection of mature mononuclear phagocytes, which may be but is not necessarily accompanied by accessory features such as necrosis. "In mice with surgical sponge-induced granulomas, and in atherosclerotic plaques, a variety of genes associated with fibrosis are expressed in transcriptome analysis: several collagen peptides and the small proteoglycans decorin and biglycan." (PMID 31736973, 2019).
hemorrhage (1 paper, 2021). Loss of blood from the vascular compartment to the exterior or into nonvascular body space as a result of rupture or severance of the blood vessels. "Furthermore, late stages of DR correspond with worsening visual acuity due to retinal damage, floaters, and hemorrhage, where the association between aqueous humor decorin concentrations and patient visual acuity was observed." (PMID 34947953, 2021).
hepatoblastoma (1 paper, 2022). Hepatoblastoma (HB) is a malignant hepatic tumor and is the most common pediatric liver cancer. "We identified high levels of IGF2 in patients enriched for Hepatoblastoma I and Hepatoblastoma II signatures, GATA1 in patients enriched for the Erythroid-like signature, POSTN in patients enriched for the DCN-high signature, and CHGA in patient 8 who was enriched in the Neuroendocrine signature." (PMID 36008377, 2022).
Hypercholesterolemia (1 paper, 2015). An increased concentration of cholesterol in the blood. "Supporting this notion, statins (3-hydroxy-3-methylglutaryl-coenzyme reductase inhibitors), which are commonly used to treat patients with hypercholesterolemia, were reported to increase decorin expression in aortic tissue." (PMID 25781946, 2015).
hyperlipidemia (1 paper, 2024). "Semiquantitative analysis of the intensity of staining and % area stained revealed that the control group had more decorin than the hyperlipidemia swines (HYP-L), contralateral tendons of the surgery group (RCI-CS), injured group (RCI-IS)." (PMID 38939871, 2024). "In our study decorin was more expressed in infraspinatus tendon tissues of control tissues than the tendons that were injured (RCI-IS, P<0.001) and hyperlipidemia tissues that did not have any surgery (HYP-L, P<0.05)." (PMID 38939871, 2024).
IgA nephropathy (1 paper, 2022). "In IgA nephropathy, the transcriptional level of decorin was increased and was mainly located in sclerotic glomeruli and fibrotic sites." (PMID 36033387, 2022). "However, it is exciting and necessary further to investigate the mechanism of decorin in IgA nephropathy." (PMID 36033387, 2022).
in situ bladder carcinomas (1 paper, 2013). "In invasive and in situ bladder carcinomas, all detected decorin mRNA was found to be localized solely to original, non-malignant stromal areas." (PMID 24146840, 2013).
in situ breast cancer (1 paper, 2011). "Higher expression of decorin in the tumor stroma was found to associate with in situ breast cancer only in patients with MAMCs (P = 0.01)." (PMID 21791066, 2011).
in situ carcinoma (1 paper, 2011). A malignant epithelial neoplasm which is confined to the epithelial layer without evidence of further tissue invasion. "Elevated levels of versican were correlated with higher tumor grade and invasiveness in carcinomas with MD and MAMCs, whereas increased amounts of decorin were associated with in situ carcinomas in MAMCs." (PMID 21791066, 2011).
inflammatory bowel disease (1 paper, 2022). A spectrum of small and large bowel inflammatory diseases of unknown etiology. "The overexpression of decorin in human colon epithelial cells resulted in increased autophagosomes and decreased apoptosis, suggesting that decorin may play a protective role in inflammatory bowel disease by increasing the autophagy of epithelial cells and decreasing apoptosis." (PMID 36033387, 2022).
intracranial aneurysms (1 paper, 2015). "Other studies have shown that decorin is up-regulated in thoracic aortic aneurysms and intracranial aneurysms." (PMID 25781946, 2015).
ischemia (1 paper, 2020). A hypoperfusion of the BLOOD through an organ or tissue caused by a PATHOLOGIC CONSTRICTION or obstruction of its BLOOD VESSELS, or an absence of BLOOD CIRCULATION. "After 20 h of 3nM decorin/vehicle treatment NRCMs were exposed to 4 h of simulated ischemia and mRNA expression changes were identified by sequencing from the cell lysate." (PMID 32731559, 2020). "Our study aimed to show the direct potential cardiocytoprotective effect of decorin in isolated cardiomyocytes in an acute in vitro model of simulated ischemia/reperfusion injury." (PMID 32731559, 2020).
ischemic stroke (1 paper, 2023). A stroke disorder caused by obstruction of blood flow to the brain, due to thrombotic (local blood clot formation) or embolic (due to a blood clot or other material traveling from another site) event. "Furthermore, we have detected Angiopoietin-like 4, which supported neurogenesis in an ischemic stroke rodent model, Decorin, which supported axon growth in the SCI model, as well as CSF1." (PMID 38025267, 2023).
juvenile idiopathic arthritis (1 paper, 2025). Juvenile idiopathic arthritis (JIA) is the term used to describe a group of inflammatory articular disorders of unknown cause that begin before the age of 16 and last over 6 weeks. "Therefore, our study aimed to evaluate the diagnostic utility of plasma proteoglycan profiles, namely, aggrecan, decorin, and biglycan, released from osteoarticular structures into the blood of children with juvenile idiopathic arthritis." (PMID 41465591, 2025). "Although concentrations of aggrecan and decorin have not previously been assessed in the blood of children with juvenile idiopathic arthritis, the concentrations of their degradation products, i.e., aggrecan neoepitopes (ARGS), dermatan sulfates (DS), and keratan sulfates (KS), have been studied." (PMID 41465591, 2025).
keratoconus (1 paper, 2016). A degenerative, structural disorder of the eye, characterized by a cone-shaped protrusion of the cornea. "The expression of stromal proteins such as vimentin, decorin and keratocan was reported to increase following keratoconus surgery." (PMID 27473120, 2016).
male infertility (1 paper, 2022). The inability of the male to effect fertilization of an ovum after a specified period of unprotected intercourse. "ECM is present between the layers of peritubular cells in the human testis, normally, and its composition and ECM amounts change in idiopathic male infertility when, for example, the DCN and BGN levels increase." (PMID 36429113, 2022).
malignant vascular tumors (1 paper, 2019). "For instance, DCN exhibits antiangiogenic activities during cutaneous wound healing, while higher DCN expression was detected in human benign tumors vs. malignant vascular tumors." (PMID 32063855, 2019).
Meester-Loeys syndrome (1 paper, 2017). "Defects in the core proteins of DS-PGs such as decorin and biglycan cause congenital stromal dystrophy of the cornea, spondyloepimetaphyseal dysplasia, and Meester-Loeys syndrome." (PMID 28346368, 2017).
meningioma (1 paper, 2020). A generally slow growing tumor attached to the dura mater. "The proteins decorin, integrin alpha-M, fibronectin, microfibrillar-associated protein 5, laminin subunit gamma-1, among others, participate in the organization of ECM and were identified exclusively or upregulated in male meningioma." (PMID 32587372, 2020).
ovarian tumor (1 paper, 2021). "This study found that the expression levels of the glycolytic genes DCN and FBP1 positively correlated with the ovarian tumor microenvironment's immune score." (PMID 34496868, 2021).
papilloma (1 paper, 2013). A benign epithelial neoplasm that projects above the surrounding epithelial surface and consists of villous or arborescent outgrowths of fibrovascular stroma. "Similarly to the healthy human breast tissue, decorin mRNA was solely localized to the original stroma around the dilated duct of the papillomas and not at all within the papillomas." (PMID 23007289, 2013).
Parkinson disease (1 paper, 2025). A progressive degenerative disorder of the central nervous system characterized by loss of dopamine producing neurons in the substantia nigra and the presence of Lewy bodies in the substantia nigra and locus coeruleus. "Strikingly, both Mirana and Pink1, whose loss in humans causes Parkinson’s disease, appear to be specifically required during development for mitochondrial size regulation and DCN circuit wiring." (PMID 40890095, 2025).
pathological myopia (1 paper, 2009). Excessive axial myopia associated with complications (especially posterior staphyloma and CHOROIDAL NEOVASCULARIZATION) that can lead to BLINDNESS. "The purpose of the study is to analyze sequences of lumican and decorin genes with pathological myopia(PM) and control subjects to verify the relationship between lumican, decorin genes and PM in Northern Han Chinese." (PMID 20339468, 2009).
phyllodes tumor (1 paper, 2014). A benign, borderline, or malignant fibroepithelial neoplasm arising from the breast and rarely the prostate gland. "To identify decorin- or periostin-binding proteins in normal and phyllodes tumor tissues, we immunoprecipitated both proteins, and subjected the immunoprecipitates to SDS-PAGE and silver staining." (PMID 25400079, 2014). "In all three cases, decorin was expressed at higher levels in normal tissues than in phyllodes tumors, whereas periostin was upregulated in phyllodes tumor, as confirmed by immunoblot analysis." (PMID 25400079, 2014). "Decorin was expressed at reduced levels in phyllodes tumor tissues, whereas periostin was upregulated; this result was validated by immunohistochemical analysis of phyllodes tumors from 35 patients." (PMID 25400079, 2014).
primary cardiomyopathies (1 paper, 2023). "In short, our analysis demonstrated that AA metabolism genes interact with the ECM proteins, such as decorin and others, directly or indirectly and might influence cardiac fibrosis in primary cardiomyopathies." (PMID 37288265, 2023).
protein misfolding diseases (1 paper, 2016). "The proteins encoded by APLP2, PTN, DCN, GPNMB, P4HB, and PDIA3, have been associated with either protein misfolding diseases or TSEs but their specific role in prion protein degradation has not been described." (PMID 26807844, 2016).
rectal cancer (1 paper, 2025). A primary or metastatic malignant neoplasm that affects the rectum. "DCN and CXCL12 were overexpressed by our chemo/CRT remodelled CAFs (CAFs 3 and 4), CAF populations like these were found to be expanded in NAC (neo-adjuvant chemotherapy) responsive rectal cancers and are known to activate anti-cancer immunity and suppress tumour progression." (PMID 40640495, 2025).
retinal detachment (1 paper, 2022). An eye emergency condition which may lead to blindness if left untreated. "In an experimental model of rabbit traumatic PVR, intravitreal injection of decorin during vitrectomy reduced the development of fibrosis and tractional retinal detachment." (PMID 36611867, 2022). "Therefore, decorin is also expected to prevent or regress neovascularization, EMT, and fibrosis in ischemic retinal diseases such as retinopathy of prematurity, proliferative DR, PVR, retinal detachment, and AMD as a TGF-β antagonist." (PMID 36611867, 2022).
retinal disease (1 paper, 2021). "Further analysis will be needed to unveil the mechanistic and functional roles of decorin in various retinal diseases." (PMID 34947953, 2021). "Decorin concentrations have also been elevated in ischemic retinas with damaged inner retinal layers and in PVR, suggesting that decorin levels are elevated during retinal disease." (PMID 34947953, 2021).
rheumatic diseases (1 paper, 2021). "Moreover, since DCN, CTSB and MMP2 also promote the inflammatory process in OA, reduction mediated by VIP again corroborates its well-known anti-inflammatory role in rheumatic diseases." (PMID 34208590, 2021).
sarcoma (1 paper, 2024). A usually aggressive malignant neoplasm of the soft tissue or bone. "Then, we analyzed the expression of biomarkers of osteoblasts (COL1A1, BGLAP and RUNX2), chondrocytes (COL2A1, COMP and SOX9) and sarcoma (POSTN and DCN), adipocyte (LPL and PPARG) and BMSCs." (PMID 39715773, 2024).
scrapie (1 paper, 2014). A fatal disease of the nervous system in sheep and goats, characterized by pruritus, debility, and locomotor incoordination. "Our results confirm the differential regulation of DCN in the MLN of sheep with natural scrapie." (PMID 24450868, 2014). "We found that gene encoding decorin (DCN), a protein located in the extracellular matrix, was overexpressed in scrapie animals, in line with previous reports of DCN upregulation at both the gene and protein level in cells isolated from scrapie-infected mouse spleen." (PMID 24450868, 2014).
skin aging (1 paper, 2021). The gradual irreversible changes in structure of skin that occur as a result of the passage of time.. "As biglycan and decorin play a role in the integrity of collagen fibers, their degradation may lead to collagen fiber decomposition, as well as skin aging." (PMID 33573338, 2021).
spondylitis (1 paper, 2017). The inflammation of a vertebra. "Our results showed the mice after receiving decorin at 3 months old were feed up to 11 months old, but weight was only significantly different at 5 and 6 months old between PG-induced spondylitis (PGISp) and control wild-type (WT) mice (both p < 0.05)." (PMID 29228588, 2017).
tongue cancer (1 paper, 2021). A malignant neoplasm affecting the tongue. "We studied their expression in epithelial cells particularly and calculated an IRS to semi-quantify the expression levels of the COL1A2 and DCN protein in normal and tongue cancer cases for comparison with CRNN." (PMID 33889206, 2021).
tubular adenoma (1 paper, 2014). A usually polypoid neoplasm arising from the glandular epithelium. "A similar trend was noticed in the colon, with strong decorin expression in normal tissue, hyperplastic adenomas and the majority of tubular adenomas, and decreased decorin expression in tubulo-villous adenomas and most adenocarcinomas." (PMID 25593993, 2014).
Ventriculomegaly (1 paper, 2016). An increase in size of the ventricular system of the brain. "It is important to recognize the possibility that some decorin-treated animals may not have developed ventriculomegaly simply because of induction failures." (PMID 27246837, 2016).
viral infections (1 paper, 2012). "This has novel implications on the postulated effector functions of Zc3hav1, in response to decorin, as it comprises a link to modulate innate cellular defenses against viral infections, and/or a mechanism to regulate endogenous RNA signaling within the tumor microenvironment." (PMID 23029096, 2012).
tumor (341 papers, 2003 to 2026). "This revealed that a higher proportion of both CD20+DCN+ B cells and CD4+DCN+ T cells interacting with tumour cells was significantly associated with shorter OS." (PMID 41392017, 2026). "This review synthesizes evidence on the roles and molecular mechanisms of major myokines-including IL-6, irisin, SPARC, oncostatin M (OSM), and decorin-in exercise-associated modulation of cancer-related inflammation and tumor progression." (PMID 41983081, 2026). "Conversely, high expression of decorin (type III—labeled in the stroma saturating the entire tumor), an antiangiogenic factor, was associated with better outcomes, although only VEGF was significantly associated with survival in the multivariate analysis." (PMID 39858283, 2025). "DCN, a known tumour suppressor, was significant across datasets and associated with improved survival, potentially by modulating the TME and promoting an anti-tumour immune response." (PMID 40349011, 2025). "This process enhances epithelial–mesenchymal transition, stemness, and angiogenesis in adjacent tumour cells, illustrating how the loss of decorin supports a pro-tumoural microenvironment." (PMID 41463344, 2025). "Downregulated were the critical genes CAV1, VWF, and DCN, suggesting loss of tumour-suppressive functions, and upregulated were SCGB2A1, CLDN4, and immune-related genes CCL3 and GZMB, promoting tumour growth and immune evasion." (PMID 41312167, 2025). "Tumorigenesis and tumor progression are marked by the loss of decorin expression, thereby relieving decorin’s inhibitory effect on TGF-βs." (PMID 38675493, 2024). "To confirm the paracrine pro-carcinogenic effects of DCN-deficient fibroblasts, we sought to test the effect of these cells on BC tumor growth in vivo." (PMID 38667295, 2024). "Experimental evidence that pyruvate dehydrogenase kinase 1 (PDK1) and lysyl oxidase (LOX) genes associated with hypoxia is associated with tumor metastasis and survival, while decorin (DCN) can inhibit tumor." (PMID 38800967, 2024). "These DCN-deficient fibroblasts also enhanced angiogenesis and orthotopic tumor growth in mice in a paracrine manner." (PMID 38667295, 2024). "This indicates that DCN-deficient fibroblasts promote tumor growth as well as the pro-metastatic processes EMT and stemness in vivo as well." (PMID 38667295, 2024). "We first showed DCN downregulation in active cancer-associated fibroblasts (CAFs) compared to their adjacent tumor counterpart fibroblasts at both the mRNA and protein levels." (PMID 38667295, 2024). "The distribution of decorin immunostaining within the tumour was significantly associated with survival time (p = 0.04) and local tumour recurrence (p = 0.02)." (PMID 37104411, 2023). "Decorin is an anti-tumor factor, and its increased levels are associated with better survival and treatment response in cancer patients, including breast cancer." (PMID 36342580, 2023). "In a study of human STS, lower decorin concentrations within a tumour were associated with a significantly shorter disease-free survival and overall survival times." (PMID 37104411, 2023). "In that study, low decorin expression within a tumour was associated with significantly reduced disease-free and overall survival rates." (PMID 37104411, 2023). "Proteoglycans in cancer is the most enriched pathway associated with MEIS1 and HOXB13 inhibition, inducing tumor suppression and DCN, LUM, and TGFBR3, as well as regulating growth factor, migration, and invasion signaling through receptor tyrosine kinases." (PMID 36661515, 2023). "Apart from the counteracting impact of decorin on muscle cachexia (discussed in the next section), its action has been associated with the restraint of tumor growth." (PMID 35454797, 2022). "We conducted a cross-sectional observation study to evaluate the association of the pathological stage with the levels of DCN in plasma or tumor surrounding tissue." (PMID 34884232, 2021).